AR (androgen receptor)
Diseases named in the same sentence as AR in open-access papers (continued):
Sharing a sentence is not in itself a finding about the gene and the disease.
prostate carcinoma (continued). "Moreover, endogenous AR expression can be induced by p65 in human prostate cancer cells, and this induction is associated with increased expression of downstream AR targets and enhanced growth and/or survival of prostate cancer cells." (PMID 23738079, 2013). "Consequently, an active AR pathway is believed to be implicated in the osteoblastic progression of prostate cancer." (PMID 24069383, 2013). "Therefore, the widely accepted supposition that androgen receptor mutations in prostate cancer result in gain of function is appealing, but mistaken." (PMID 22403669, 2012). "αvβ6 expression is associated with inflammation, and the β6 subunit is increased in cases of benign prostatic hypertrophy as well as in prostate cancer, where αvβ6 has been implicated in controlling prostate cancer growth in conjunction with the androgen receptor." (PMID 24213501, 2012). "Previous studies on AR mutations have either simply reported the presence of specific mutations in prostate cancer biopsies or analyzed a select few examples using incompatible methodology, thus precluding meaningful comparison of the consequences of the mutations." (PMID 22403669, 2012). "In addition, recent results have shown that B-DIM treatment of prostate cancer cells in vitro or B-DIM intervention in patients with prostate cancer led to the nuclear exclusion of AR associated with activation of miR-34a." (PMID 23056607, 2012). "Taken together, these results indicate that salinomycin reduces the expression of key prostate cancer oncogenes and AR signalling as well as causes alterations in steroid biosynthesis, cell-cycle checkpoint regulation, AhR signalling and oxidative stress response in prostate cancer cells." (PMID 22215106, 2012). "Finally, G202-based delivery of the thapsigargin analog causes marked reduction of expression of the androgen receptor (AR) in prostate cancer cells and the estrogen receptor (ER) protein in breast cancer." (PMID 22837432, 2012). "In a prostate cancer model using transgenic mice, the onset of prostatic tumorigenesis as well as tumor growth was significantly potentiated by introduction of an AR point mutation (AR T877A) into the prostate and genetic screening of mice identified Wnt-5a as an activator." (PMID 22325146, 2012). "We further hypothesized that the combination of B-DIM with casodex may have a synergetic effect on the inhibition of AR expression and induction of apoptosis in prostate cancer cells, which may be associated with the activation of AMPK." (PMID 23056607, 2012). "Type of prostate cancer in which the AR mutations were detected." (PMID 22403669, 2012). "Determining the prevalence of AR variants in different clinical states of prostate cancer has been challenged by requirements for well-preserved frozen tissue samples for transcript-based analyses, and the lack of antibodies capable of specifically detecting most AR variant proteins." (PMID 22114732, 2011). "As for the underlying mechanisms of TPL2-mediated ADI prostate cancer growth, a question is whether this action requires AR expression and activity." (PMID 21267413, 2011). "Moreover, they revealed that inhibition of the PI3K signaling pathway restores AR signaling in PTEN-deficient prostate cancer cells, suggesting that resistance to castration can be reversed." (PMID 22110995, 2011). "For example, point mutations in the AR gene identified in metastatic cells from patients and from AI prostate-cancer cell lines could be activated by progesterone and estrogen." (PMID 24212771, 2011). "Also, a small-molecule inhibitor of the amino-terminus domain of the androgen receptor causes regression of castrate-recurrent prostate cancer." (PMID 22228887, 2011). "In males, a shorter CAG repeat length in the AR gene is associated with prostate cancer." (PMID 22151998, 2011).
prostate carcinoma (continued). "Prostate cancer is initially dependent on androgens for growth, and androgen ablation therapy causes regression of the tumor, likely through inactivation of the transcription of the AR target genes." (PMID 19855844, 2009). "Furthermore, overexpression of SMRT or restoring the association of SMRT with AR on AR target genes by MEK inhibitors correlates with the ability of antiandrogens to inhibit prostate cancer cell growth." (PMID 19383165, 2009). "Our findings suggest that loss of cystatin C and overexpression of AR may be two cooperative events in the progression of prostate cancer." (PMID 19956729, 2009). "Mutations in the coding region of AR have also been found in antiandrogen treated prostate cancers." (PMID 18673534, 2008). "Since it has been shown that androgen-independent prostate cancer is heterogeneous and multifocal, it is possible that castration-refractory tumors derive from different combinations of the AR amplification, AR mutations and deregulated signaling pathways." (PMID 18218096, 2008). "In this study, we examined whether the association between the rs266882 genotype and prostate cancer risk or baseline PSA levels was modified by AR CAG repeat length." (PMID 18827812, 2008). "Furthermore, androgen independence is a feature of terminal stages in metastatic prostate cancer and the loss of AR expression in those cells appears to be at the transcriptional level rather than involving deletion or mutation mechanisms." (PMID 19936097, 2007). "Two of the AR-occupied regions disclosed by ChIP Display were near loci previously linked to PCa: (i) the hereditary prostate cancer 1 (HPC1) locus, which has been mapped to 1q24-25; and (ii) the 8q24 locus, recently linked to PCa through admixture mapping in African American men." (PMID 17553165, 2007). "Importantly, siRNA-directed silencing of AR allows inhibiting the synthesis of overexpressed wild type receptors, as well as mutated or stabilized isoforms that can be encountered in advanced prostate carcinomas." (PMID 17925854, 2007). "Overall, the results suggest that AR might be a factor in the regulation of the susceptibility of prostate cancer cells to PL-induced apoptosis." (PMID 17262078, 2007). "In prostate cancer C/EBPα was detected at low levels throughout the cancers and in advanced prostate cancer C/EBPα expression was associated with decreased expression of AR and PSA." (PMID 16774685, 2006). "The mechanism(s) for the loss of AR expression both in prostate cell lines and prostate cancer tissue are not completely understood and expression may vary in the same patient at different sites of recurrence." (PMID 16774685, 2006). "Compared to full-length cyclin D1, the cyclin D1b variant was significantly deficient in its ability to repress AR-dependent expression of the prostate specific antigen (PSA) mRNA expression in prostate cancer cells, a target gene used clinically to monitor prostate growth and progression." (PMID 16863592, 2006). "Although ErbB receptors have been implicated in the progression of prostate cancer, little is known about proteins that may mediate their interactions with the androgen receptor (AR)." (PMID 15583694, 2005). "Because androgen-independent prostate cancers often become resistant to antiandrogens and AR mutations can result in stimulation by other steroids, including antiandrogens, we tested the effect of the antiandrogen flutamide on DHT-stimulated growth in control and CAsE-PE cells." (PMID 16140617, 2005). "Interestingly, C/EBPβ has also been implicated in prostate cancer progression, where it may interact with androgen receptor (AR) signaling to modulate tumor growth and therapy response." (PMID 41596564, 2026).
prostate carcinoma (continued). "On the other hand, pTVG-AR, encoding the ligand-binding domain of androgen receptors, targets the androgen receptor (AR), which plays a pivotal role in the development and progression of prostate cancer, particularly in castration-resistant prostate cancer (CRPC)." (PMID 39833784, 2025). "However, studies aimed at evaluating adverse clinical impacts of AR inhibitors in prostate cancer patients evidenced a number of adverse events associated with the Central Nervous System functions, such as amnesia, unspecified cognitive disorders, memory impairment and state of confusion." (PMID 40399259, 2025). "In prostate cancer, aberrant DNA methylation patterns have been associated with disease aggressiveness and poor prognosis, while deregulated noncoding RNAs, such as microRNAs and long noncoding RNAs, have been shown to modulate AR signaling and other oncogenic pathways." (PMID 41200281, 2025). "Finally, AR was also associated with prostate cancer susceptibility in OMIM." (PMID 41254939, 2025). "Another molecular link is hormone receptors: androgen receptor (AR) gene variations can cause mild androgen insensitivity, presenting as oligospermia and subtle metabolic issues; these same AR variants could influence prostate cancer risk." (PMID 40507691, 2025). "Given that AR loss is a key feature of therapy-resistant PCa, this model allowed us to examine whether NO’s ability to regulate ER stress and inhibit tumor growth is consistent in AR-negative prostate cancer cells." (PMID 41198652, 2025). "Following lung cancer, prostate cancer is the most common cause of cancer in adult men, with metastatic castration-resistant prostate cancer remaining a leading cause of death in this population despite increased screening protocols and the development of androgen receptor antagonists." (PMID 39335124, 2024). "We hypothesize that the AR/DPYSL5/EZH2/PRC2 axis is a novel mechanism underlying prostate cancer progression to t-NEPC, and it is important to further elucidate the theranostic potential of DPYSL5 and explore any pharmacological strategies that could manipulate its expression." (PMID 38238517, 2024). "Likewise, men with prostate carcinoma receiving androgen deprivation therapy show a higher risk of developing insulin resistance and hyperglycemia, consistent with our findings of reduced AR expression level in I-Res iMyos." (PMID 38032738, 2024). "However, the current literature regarding the impact of estrogens in prostate cancer cell proliferation has been criticized, since the most common human prostate cancer in vitro model (LNCaP cells) have a mutated androgen receptor which is activated by estradiol and has low ER expression overall." (PMID 39840030, 2024). "In our study, the loss of CLDN3 expression observed in CRPC cells and tumors could be explained, at least in part, by the loss of CLDN3 control by AR, since it has been demonstrated that AR regulates a different expression profile in androgen-sensitive and independent prostate cancer cells." (PMID 36614243, 2023). "Additionally, mutations and alterations in the relative expression of AR may contribute to the progression of prostate cancer and the failure of endocrine therapy." (PMID 37175938, 2023). "Treatment-induced AR alterations, including AR alternative splice variants (AR-Vs), have been extensively linked to harboring roles in primary and acquired resistance to conventional and next-generation hormonal therapies in prostate cancer and therefore have gained momentum." (PMID 36983083, 2023). "Men diagnosed with prostate cancer are at risk for competing morbidity and mortality due to cardiometabolic disease given their advanced age at diagnosis, high prevalence of pre-existing risk factors, and receipt of systemic therapy that targets the androgen receptor (AR)." (PMID 37705024, 2023).
prostate carcinoma (continued). "However, the range of mechanisms by which AR controls physiologic signaling networks, how they are dysregulated during disease progression, and the complex network of pathways underlying the emergence of resistant prostate cancer are not fully understood." (PMID 37874216, 2023). "Moreover, the cooperative function of SFPQ and NONO could increase the expressions of genes associated with prostate cancer such as AR." (PMID 36982591, 2023). "Furthermore, NF-κB-induced resistance to ADT may be mediated by the excessive activation of AR and production of AR variant-7 in prostate cancer cells." (PMID 37375731, 2023). "A proportion of these patients are primarily resistant to the treatment, which may be caused by AR heterogeneity in prostate cancer and other alterations in enzymes crucial for the conversion of extragonadal precursors to potent androgens, such as the 3βHSD1 germline variant." (PMID 35864113, 2022). "SIRT7 activity displays a crucial role in prostate cancer where its depletion in vitro and in vivo causes inhibition of cell proliferation, autophagy and invasion via the downregulation of androgen receptor (AR) pathway mediated by small mother against the decapentaplegic 4 (SMAD4) protein." (PMID 35328633, 2022). "In particular, CAG repeat polymorphism of AR gene could influence the transcriptional activity of testosterone target genes, consequently providing a multitude of effects on bone density, body composition, behavioral aspects and even prostate cancer." (PMID 35408895, 2022). "Thus, prostate cancer patients with anti-AR treatment may be less susceptible to SARS-CoV-2 infection." (PMID 35017320, 2022). "Since antiapoptotic genes belong to the target genes of NF-κB, this implies a potential survival advantage for metastasizing prostate cancer cells caused by the treatment leading to the notion that a combined anti-AR/anti-NF-κB treatment might outperform the standard antiandrogen treatment." (PMID 36551650, 2022). "Consequently, IRC117539-induced AR depletion achieves selective and potent loss-of-viability in AR-positive prostate cancer cell lines, suggesting that pharmacologic manipulation of sumoylation may be a viable treatment strategy in solid tumors as well." (PMID 35269436, 2022). "Thus, it will be interesting to investigate in future studies whether the Kindlin-2-Src-AR signaling axis delineated in the current study also plays a role in prostate cancer and other human diseases associated with aberrant AR signaling." (PMID 35595729, 2022). "Notably, GHSROS modulates the expression of PPP2R2C, the loss of which may drive androgen receptor pathway-independent prostate tumor progression in a subset of prostate cancers." (PMID 33585078, 2021). "Sialylated blood group antigen Sialyl Lewis X (SLeX) influences prostate cancer progression through various mechanisms as well as the cancer-associated sialyl-Tn glycan (sTn), which affects prostate cancer cell adhesion and whose expression is shown to be regulated by AR." (PMID 33572160, 2021). "Furthermore, Gemin4 is known to be regulated by the AR and associates with prostate cancer progression, which is highly relevant in the context of prostate cancer and CaMKK2 biology as the AR is also a major driver of CaMKK2 expression, disease progression and biology." (PMID 34725334, 2021). "Notably, a high frequency of AR mutation was observed in prostate cancer plasma samples." (PMID 33397889, 2021). "Moreover, ATM signaling can also be upregulated in cancer cells that have already evaded cell apoptosis through other mechanisms, as seen in melanoma through upregulation of melanoma-associated antigen-encoding (MAGE) genes as well as in prostate cancer by activation of the Androgen receptor (AR)." (PMID 34068084, 2021). "Interestingly, deficiency or inhibition of androgen receptor function in prostate cancer cells could induce TCIPA in vitro." (PMID 34322381, 2021).
prostate carcinoma (continued). "Indeed, the activation of the PI3K-Akt-mTOR pathway induced by PTEN loss and anti-AR treatments may promote prostate cancer cells proliferation and survival in androgen-reduced conditions." (PMID 35011901, 2021). "While androgens are both circulating and produced in tissue, elevated tissue DHT, implicated in AGA and benign prostatic hyperplasia, and prostate cancer, as well as AR sensitivity, may be better predictors of COVID-19 severity than circulating androgen levels." (PMID 33643746, 2021). "Moreover, melatonin might impair the interrelations between the NF-κB and androgen receptor splice variant 7, thus detaining the development of resistance to androgen depletion therapy in advanced prostate cancer." (PMID 35008896, 2021). "However, during the progression of prostate cancer, the acquisition of this androgen independence can occur via loss of androgen receptor expression or via other mechanisms that make the receptor active independently of androgens, i.e., gain-of-function mutations in the receptor." (PMID 34572036, 2021). "Finally, the lower expression of AR-v567es in EpCAMpos CTCs from patients with mCRPC together with its respective enrichment in NEPC suggests that this AR variant may be implicated in prostate cancer lineage plasticity." (PMID 34168263, 2021). "Furthermore, a recent study shows that activities of c‐Myc and AR pathways are significantly correlated in prostate cancer, while c‐Myc depletion leads to decreased expression of full‐length AR, as well as of several AR splice variants involved in AR‐targeted therapy resistance." (PMID 32310340, 2020). "Moreover, Sam68 was also demonstrated to bind an ESE located near the cryptic exon 3b 3′ splice site of the androgen receptor mRNA, promoting the inclusion of exon 3b in the transcript and its translation into the androgen receptor V7 variant in the LNCaP prostate cancer cell line." (PMID 32596243, 2020). "This systematic review and meta-analysis examines 11 randomized clinical trials to see whether therapy with androgen receptor inhibitors (ARIs), such as enzalutamide, apalutamide, or darolutamide, is associated with an increased risk of falls and fractures in men with prostate cancer." (PMID 33201234, 2020). "Fourthly, similar to prostate cancer, it has been shown that expression of AR splice variant such as AR-V7 lacking all or a portion of ligand binding domain results in constitutively active AR and regulates a transcriptional program distinct from that of full-length AR." (PMID 32850312, 2020). "Therefore, peer-reviewed publications on prostate cancer genetics in African populations have reported genetic variants that contribute to elevated circulating androgens, including androgen reduced clearance and upregulated activity of androgen receptor." (PMID 33659210, 2020). "Interestingly, AR-V7, as AR splice variant in prostate cancer, is the most extensively researched among tumors and circulating tumor DNAs; it is widely accepted that monitoring and inhibiting AR-V7 is a clinical priority in prostate cancer treatment." (PMID 32982970, 2020). "As an AR inhibitor, Enz can reduce the proliferation and death of prostate cancer cells, and it also can block the malignant progression caused by AR-mediated LINC01503 in NPC, which may provide a potential drug target for individualized treatment of NPC patients." (PMID 32661324, 2020). "Thus, loss of ESRP expression may provide a molecular explanation why AR positive prostate cancer cells show increased susceptibility to EMT in response to ADT, and so is relevant to consider with regard to therapy." (PMID 31478829, 2019). "In addition, AR has been implicated in other diseases, such as prostate cancer." (PMID 31395886, 2019).